PML (PML nuclear body scaffold)
Diseases named in the same sentence as PML in open-access papers (continued):
Sharing a sentence is not in itself a finding about the gene and the disease.
infection (continued). "Viral genome colocalization to PML-NBs only occurs in neurons exposed to type I interferon at the time of infection." (PMID 35772067, 2022). "Recently, we gained knowledge showing that several PML-NB factors are essential to support virus replication and productive infection, explaining why the viral genomes of HAdV are found juxtaposed to PML-NBs." (PMID 35699431, 2022). "Common conclusion from these studies is that PML-NBs reorganization has a determining role during infection." (PMID 35699431, 2022). "Infection with the herpes simplex virus HSV-1 leads to the formation in the host cell of viral DNA-containing PML nuclear bodies (vDCP NBs), PML-bodies containing the double-stranded DNA of the herpes virus." (PMID 34072343, 2021). "Small ubiquitin-related modifier-dependent dynamics of PML NBs shapes the outcome of infection with HSV-1, an alphaherpesvirus of the Herpesviridae family which generally causes oral sores." (PMID 34513832, 2021). "Consistently, progressive lytic infection was found to reduce the number of PML NBs within infected cells with concomitant increase in the puncta size without triggering complete disassembly of these speckled structures." (PMID 34513832, 2021). "PML restricts HIV-1 in MEFs during early post-entry stages of infection and contributes to transcriptional silencing of integrated provirus." (PMID 33807177, 2021). "Many reports have enunciated crucial interplays between PML NBs as the hubs of cellular intrinsic immune defenses and viral countermeasures to establish infection and to ensure perpetuation." (PMID 34513832, 2021). "Western blotting analysis indicated that the PML isoforms were upregulated during the late stage of infection." (PMID 34888375, 2021). "EMCV infection of PML−/− mouse embryonic fibroblasts (MEFs) resulted in higher viral replication and protein production." (PMID 33807177, 2021). "Of note, a perfect colocalization of viral DNA with PML-NBs after infection of human fibroblasts with RCMV was observed suggesting efficient silencing of RCMV gene expression in the absence of PML-NB antagonization." (PMID 34370791, 2021). "In ZIKV-infected hBMECs, NS5 proteins, display nuclear colocalization with PML NBs, which increase in size as the infection progresses." (PMID 33807177, 2021). "The phase of infection between the initial viral transcription and replication at the PML bodies and the generation of an infected cell that maintains extrachromosomal viral genomes is termed “establishment”." (PMID 34578427, 2021). "Like many DNA viruses, HPVs initiate infection at the PML nuclear bodies despite the fact that these bodies contain many interferon-responsive anti-viral factors." (PMID 34578427, 2021). "Like other RNA viruses, PML exerts antagonistic effects during infection with the Orthomyxoviridae family member influenza A virus in a viral strain-specific manner." (PMID 34513832, 2021). "The RING finger protein Z of LCMV, an Arenaviridae family member which transmits zoonotically to human leading to aseptic meningitis, induces redistribution of PML from nuclear condensates to cytoplasmic aggregates during infection." (PMID 34513832, 2021). "Quantitative reverse transcription PCR (RT-qPCR) analysis showed significant upregulation of PML isoforms and PML-NB-associated genes (Daxx and SP100) at 36 and 48 h post-infection (hpi)." (PMID 34888375, 2021). "Here, we report that PML-NBs also serve as a distinct barrier against cross-species infections of rodent CMVs." (PMID 34370791, 2021). "During infection with the wild type virus, the PML NB association of vDNA is transient as the HSV-1 protein ICP0 counteracts this quiescence by dispersal of PML NBs." (PMID 34513832, 2021). "A GFP-expressing recombinant KSHV showed that knockdown of PML or Sp100 gave a higher number of GFP positive cells in the primary infection, indicating the restrictive effects of ND10 components on the incoming KSHV." (PMID 33546431, 2021).
infection (continued). "To assess the role of E2A SUMOylation in Sp100A positioning in PML-NBs, we transfected cells with pYFP-Sp100A prior to infection with HAdV wt and HAdV E2A SCM." (PMID 32184235, 2020). "SUMOylated E2A interacts with PML (top), and PML-NBs localize adjacent to HAdV RCs in HAdV wt infection (31, –, 33, 36) (top)." (PMID 32184235, 2020). "In this review, we are discussing the role promyelocytic leukemia (PML) nuclear bodies (NBs) play during infection with human papillomavirus (HPV)." (PMID 32154186, 2020). "HSV1 ΔICP0 parental genome have limited gene expression as it remains entrapped by PML-NBs upon infection of the cell nucleus." (PMID 33598438, 2020). "The formation and functions of PML-NBs are often affected by DNA viruses during infection, including PyVs." (PMID 32203554, 2020). "Many viruses, specifically nuclear-replicating viruses, have been shown to target PML NBs as a critical step for establishing productive infection." (PMID 32154186, 2020). "Our immunofluorescence data confirmed previous observations that Sp100A localizes in PML tracks during HAdV wt infection." (PMID 32184235, 2020). "Our findings reveal that E2A is a novel interaction partner of PML and Sp100A during infection, indicating that E2A plays a role in HAdV manipulation of PML-NB functions." (PMID 32184235, 2020). "HIRA binds ISGs loci to promote their transcriptional upregulation, further stimulating the innate immune defenses upon HSV1 infection; in this way, undisrupted PML-NB are able to induce an IFN response upon HSV1 ΔICP0 infection." (PMID 33598438, 2020). "We will compare with how other viruses interact with PML NBs and the outcome for establishment of infection." (PMID 32154186, 2020). "In order to better study the interactions of HPV particles and PML NBs and their outcomes for infection, pseudoviral and quasiviral vectors have recently been more widely used over overexpression systems." (PMID 32154186, 2020). "In this paper we found that the number of IE1 foci colocalizing with PML increases as infection progresses, as indicated by a higher Mander’s coefficient of colocalization (MCC) at 72h of infection, compared to 24h." (PMID 32658923, 2020). "They restrict HSV-1 gene expression and replication by forming structures called viral DNA-containing PML-NBs (vDCP NBs), which is an intrinsic antiviral response strategy of preventing lytic infection." (PMID 32545507, 2020). "Subsequent detection of E2A revealed that E2A interaction with PML during infection depends on E2A SUMO PTM (right, lanes 3 and 4)." (PMID 32184235, 2020). "Infection with HAdV wt results in higher levels of Sp100A protein (top) and PML-independent interactions between E2A and Sp100A (top)." (PMID 32184235, 2020). "Recent reports have shown the HIRA H3.3 chaperone complex localizes at PML-NBs in response to infection with replication-defective herpesviruses to promote the assembly of viral genomes into chromatin for subsequent epigenetic silencing." (PMID 30901352, 2019). "ICP0 induces PML degradation at the early stage of infection to release the viral genomes entrapped within PML-NBs." (PMID 31781083, 2019). "Recent studies have reported that HIRA accumulates at PML-NBs in response to infection with replication-defective herpesviruses (HSV-1 and HCMV)." (PMID 30901352, 2019). "HIRA recruitment to PML-NBs under these infection conditions occurred in a JAK-dependent manner and was significantly impaired during WT HSV-1 infection." (PMID 30901352, 2019). "Often, large DNA viruses disassemble and reorganize PML NBs to counteract their intrinsic antiviral activity and support establishment of infection." (PMID 30802273, 2019). "Replication-defective herpesviruses promote the activation of PRRs that induce innate immune defences and cytokine secretion, which likely accounts for the stable localization of HIRA at PML-NBs observed under replication-defective infection conditions." (PMID 30901352, 2019).
infection (continued). "When 200 or 500 nM bortezomib was added prior to infection, the punctate PML staining was sustained during infection (open triangles)." (PMID 31088925, 2019). "We therefore identify that virus-induced cytokine signalling cascades to play an important role in the spatiotemporal localization of HIRA at PML-NBs during infection of normal diploid cells." (PMID 30901352, 2019). "These intracellular host defences are antagonized by the HSV-1 ubiquitin ligase ICP0, which disrupts the stable recruitment of HIRA to infecting viral genomes and PML-NBs at spatiotemporally distinct phases of infection." (PMID 30901352, 2019). "Along with nuclear DNA sensor IFI16, we detected ATRX and PML recruitment to viral DNA by 15 min post infection (mpi), almost immediately upon nuclear entry." (PMID 30465651, 2018). "PML is an antiviral TRIM protein, and PML nuclear bodies are routinely found to be altered during infection by viruses that replicate in the nucleus." (PMID 29717008, 2018). "PML KO mice become sensitive to infection including vesicular stomatitis virus (VSV), rabies virus, and arenavirus lymphocytic choriomeningitis virus (LCMV)." (PMID 29922292, 2018). "EMCV infection induces the transfer of PML to the nuclear matrix and leads to an increased PML-NB size." (PMID 29922292, 2018). "PML transferring from the nucleoplasm to the nuclear matrix induced by EMCV infection led to a bigger size of PML-NBs." (PMID 29922292, 2018). "The L2/vDNA complex eventually resides at promyelocytic leukemia (PML) nuclear bodies, which are thought to support the early viral gene expression that is required for the establishment of infection." (PMID 30181457, 2018). "Infection with murid herpesvirus 4 (also called murine herpesvirus 68 or MHV-68) also results in the dissolving of PML-NBs." (PMID 29065450, 2017). "In human fetal lung fibroblasts (IMR90), HIRA localized to PML bodies in response to infection with UVHCMV or HSV in1318." (PMID 28981850, 2017). "In order to characterize the role of PML during infection in vivo, we first infected wild-type (WT) and PML knockout mice with Listeria (EGD strain)." (PMID 28074026, 2017). "On infection with several DNA viruses, this pathway is influenced by the activity of components of subnuclear structures, PML bodies, such as PML and Sp100 and, interestingly, another histone H3.3 chaperone, DAXX." (PMID 28981850, 2017). "In contrast to PML’s established action against viruses, a single study mentioned that PML knockout mice are more sensitive to infection by Listeria monocytogenes." (PMID 28074026, 2017). "In these cells, PML inhibits the early postentry stages of infection and also promotes the transcriptional silencing of the integrated provirus." (PMID 28656178, 2017). "In a similar fashion, the vFGARAT of RRV, ORF75, induces degradation of both PML and SP100 upon recombinant expression, and infection with RRV leads to an almost complete loss of these ND10 components in infected cells." (PMID 29065450, 2017). "PML bodies have been shown to be important for efficient infection from reporter-expressing HPV16 pseudoviruses, as well as authentic BPV virions, suggesting that the vDNA is actively targeted to these sites by L2 upon infection." (PMID 29207511, 2017). "We and others recently reported that both murine PML (mPML) and human PML (hPML) strongly restrict the early stages of infection by HIV-1 and other lentiviruses when expressed in mouse embryonic fibroblasts (MEFs)." (PMID 28656178, 2017). "During primary infection, the viral minor capsid protein, L2, delivers the viral DNA to the ND10 body by interaction with the PML protein, and this is important for efficient infection." (PMID 28968443, 2017). "Among the major nuclear components that influence the infection process the promyelocytic leukemia (PML) nuclear bodies (NBs) play a major role as nuclear relays of the intrinsic antiviral response." (PMID 27618691, 2016).
infection (continued). "In infected cells the time when US3 starts to express (3–6 h post infection) overlaps with the time when degradation of PML and Sp100 is nearly completed." (PMID 27048561, 2016). "An elegant study by Gunther and colleagues revealed that the PML factor Sp100 is involved in the regulation of the H3K27me3 level on lytic promoters during de novo infection." (PMID 27606464, 2016). "Similar to HSV-1, a member of the alpha-herpesvirus family, modulation of PML-NBs has been shown with the beta-herpesvirus family member HCMV during immediate early phases of infection." (PMID 27782081, 2016). "We found that overexpression of mPML in PML-KO MEFs strongly decreased the GFP MFI following infection by HIV-1NL-GFP and SIVmac-GFP (up to 13.3-fold and 22.3-fold, respectively)." (PMID 27000403, 2016). "Next, WT and PML-KO MEFs were treated with the blocking antibody (650 ng per 20,000 cells) prior to infection with increasing doses of HIV-1." (PMID 27000403, 2016). "As a consequence, ICP0 induces the destabilization of PML-NBs and centromere chromatin, which contributes to creation of a nuclear environment suitable for lytic infection." (PMID 27618691, 2016). "It has also been reported that constitutive overexpression of PML in mouse cells induces resistance to infection by RNA viruses, such as vesicular stomatitis virus (VSV) and influenza A." (PMID 27000403, 2016). "Following the original study, using HSV-1 the group of Everett extensively investigated the mechanisms of how incoming viral genomes interact with PML-NBs upon infection, making this virus the best-studied model." (PMID 27782081, 2016). "Initially the group found that ICP4, a viral transcription regulator encoded in the immediate early gene, forms nuclear foci that are co-localized with or juxtaposed to PML-NBs during immediate early phases of infection." (PMID 27782081, 2016). "In summary, our study deciphered a major role of the PML-NBs in the antiviral responseagainst the infection by a nuclear replicating virus." (PMID 28357326, 2016). "Nevertheless, our infection experiments showed that the overexpression of each of the single PML isoforms I to VI moderately reduces HIV reporter virus infectivity in HFFs by approximately 2- to 3-fold on average." (PMID 26703718, 2015). "Upon infection, we found that the knockdown of PML (shPML) enhanced the infectivity of all three reporter viruses independently of the promoter when compared to control HFFs (shC)." (PMID 26703718, 2015). "Although we cannot associate the observed PML and SUMO phenotypes with a benefit to either the host or the pathogen, this report is the first to demonstrate that bacterial pathogens can alter PML-NB number during infection." (PMID 25848798, 2015). "There was a strong correlation between the infection progression and the upregulation of PML-mRNA level." (PMID 25962098, 2015). "We found that the knockdown of PML in primary human fibroblasts enhanced not only HIV-1 infectivity but also the infection of the retroviruses SIV, MLV and MPMV." (PMID 26703718, 2015). "For instance, a PML-associated ATRX-DAXX complex has been demonstrated to chromatinize and transcriptionally repress herpesviruses during infection, while a HIRA-UBN1 complex is thought to coordinate senescence-associated heterochromatinization." (PMID 25665578, 2015). "Small hairpin RNA-mediated PML knockdown in human fibroblasts reduced ISG induction by treatment of interferon-β or infection with UV-inactivated HCMV." (PMID 25812002, 2015). "We also found an early relocalization of PML to the cytoplasm during retroviral infection, suggesting a PML-mediated block to infection during the early phases of infection in the cytoplasm of infected cells." (PMID 26703718, 2015).
infection (continued). "At protein level, it was observed that DENV-2 infected A549 cells showed the typical pattern of PML-NBs at early stages of infection (1–6 h p.i.)." (PMID 25962098, 2015). "For instance, PML−/− mice exhibit increased viral load after infection with lymphocytic choriomeningitis virus (LCMV) and vesicular stomatitis virus (VSV)." (PMID 26101541, 2015). "Quantitative PCR analysis of HIV cDNA in infected cells revealed that PML restricts infection at the level of reverse transcription." (PMID 26703718, 2015). "As IFIX interaction with PML within nuclear puncta is already observed in uninfected cells, we do not expect that punctate formation is specifically induced by infection." (PMID 25665578, 2015). "Further, efficient PML protein knockdown by shRNA lentiviral transduction was used to determine PML-NBs relevance during infection." (PMID 26389938, 2015). "Similar to the situation in human fibroblasts, we found that the knockout of PML already enhanced the number of late RT products as well as 2-LTR circles upon infection of MEFs." (PMID 26703718, 2015). "In co-IP assays performed at 8 h after infection, PML was found to interact with STAT1, STAT2, HDAC1, and HDAC2 in UV-HCMV-infected cells but not in uninfected cells." (PMID 25812002, 2015). "It is established that upon infection PML nuclear bodies reform directly adjacent to the site at which nuclear-replicating viruses deposit their nucleic acid genome." (PMID 25665578, 2015). "Our findings indicate that PML-NB number and SUMOylation of cellular proteins are altered during infection with Shigella, and these cellular changes require T3SS effectors." (PMID 25848798, 2015). "This was expected as the HSV-1 viral E3 ubiquitin ligase protein, ICP0, targets PML for degradation early in infection and disperses PML body components." (PMID 25665578, 2015). "We recently demonstrated that infection of fibroblasts with HVS results in restriction of immediate-early gene expression, which can be alleviated by siRNA mediated knock down of PML; PML is thus also a restriction factor for HVS infection." (PMID 24453968, 2014). "Overcoming PML-NB-mediated cellular intrinsic immunity is essential to allow the initial transcription and replication of the herpesvirus genome after de novo infection." (PMID 25268162, 2014). "Infection of primary human fibroblasts with rhesus macaque cytomegalovirus (RhCMV) revealed an initial accumulation of rhIE1 at PML-NBs followed by a dispersal of NBs." (PMID 25412268, 2014). "Shortly upon infection, PML can be found to be recruited to viral genomes in a manner contingent upon its SUMOylation, as forms that cannot be SUMOylated fail to appreciably respond to the nuclear entry of viral DNA and remain positionally stable." (PMID 25513827, 2014). "IE1 transiently co-localizes with PML-NBs during the first 2–4 hours after infection but subsequently induces disruption of these structures." (PMID 25412268, 2014). "Disruption of PML-NBs is essential for efficient infection and the lytic replication of a number of DNA viruses, including herpesviruses." (PMID 25268162, 2014). "We recently demonstrated that PML acts as a restriction factor for infection with the gammaherpesvirus HVS." (PMID 24453968, 2014). "Early during infection, ICP0 colocalizes with PML and induces the proteasomal degradation of PML as well as the loss of certain forms of Sp100." (PMID 25513827, 2014). "The association between PML NBs and the genomes of HCMV and adenovirus is also most readily observed at early times of infection or with mutant viruses that fail to express regulatory proteins that would normally disrupt PML NBs." (PMID 23825941, 2013).